IL15 (interleukin 15)
Diseases named in the same sentence as IL15 in open-access papers (continued):
Sharing a sentence is not in itself a finding about the gene and the disease.
skin tumors (2 papers, 2020 to 2026). "IL-15 is produced ubiquitously by several cell types, such as dendritic cells and keratinocytes in the skin, where skin tumors or typical skin lesions infiltrated with ATL cells were commonly observed in ATL patients." (PMID 32210945, 2020).
staphylococcal infection (2 papers, 2018 to 2023). An infection caused by Staphylococcus. "This critical role of NK cells was also seen in a study with mice models of IL-15 KO deficient in NK cells and wild type mice depleted of NK cells, which were highly susceptible to pulmonary staphylococcal infection." (PMID 37371793, 2023). "Thus, although IL-15 is a cytokine that is important for innate immune responses that are protective in the case of staphylococcal infections, aIL-15ab ought to be a safe addition to antibiotics." (PMID 29440371, 2018).
thymoma (2 papers, 2015 to 2023). A neoplasm arising from the epithelial cells of the thymus. "These authors identified eight cytokines that were significantly changed among MG patients with thymoma (i.e., IL-4, IL-8, IL-15, eotaxin, macrophage inflammatory protein-1α, macrophage inflammatory protein-1β, VEGF and IL-1b)." (PMID 25889429, 2015).
vascular dementia (2 papers, 2015 to 2021). A degenerative vascular disorder affecting the brain. "In vascular dementia patients, IL-15 was higher in those with than without infection." (PMID 33723589, 2021). "Contradicting the inflammatory hypothesis, they found lower serum levels in AD compared to healthy subjects and patients with vascular dementia and, treatment with acetylcholinesterase inhibitor (AChEI) had no influence on IL-15 concentrations in AD patients." (PMID 25710473, 2015).
viral hepatitis (2 papers, 2021 to 2023). An acute or chronic inflammation of the liver parenchyma caused by viruses. "IL-15 is present constitutively in the hepatic microenvironment, and upregulated in viral hepatitis." (PMID 33692781, 2021).
Wilms tumor (2 papers, 2022). An embryonal neoplasm characterized by the presence of epithelial, mesenchymal, and blastema components. "To evaluate the tumor toxic effects of uncultured and cytokine (IL-2 and IL-15) coculture NK cells, we have chosen two types of tumor cell lines including human Wilms' tumor (G401 and SK-NEP-1) and as the targets in antitumor assay." (PMID 36213822, 2022). "IL-2 combined with IL-15 enhanced the expression of NKG2D receptor to inhibit Wilms’ tumor via the mitogen-activated protein kinase (MAPK) signaling pathway." (PMID 36601109, 2022).
X-linked severe combined immunodeficiency (2 papers, 2019 to 2021). "X-linked severe combined immunodeficiency (SCID-X1) is caused by deficiency of the common cytokine receptor gamma chain, a component of multiple cytokine receptors (IL2, IL4, IL7, IL9, IL15 and IL21) responsible for many aspects of lymphoid development and function." (PMID 33712608, 2021).
acne (1 paper, 2020). An inflammatory process of the sebaceous glands which is characterized by comedones, nodules, papules and/or pustules on the skin. "Among cytokines, IL-15 was decreased in the DTCV acne group, while IL-1β was increased in the female subjects in the other PI groups compared with the control group." (PMID 31951642, 2020). "The present study is the first to evaluate the serum levels of IL-1α, IL-1β, IL-6, IL-8, IL-12β, IL-15, TNF-α, and granulocyte-macrophage colony-stimulating factor in acne subjects compared with the levels in healthy controls." (PMID 31951642, 2020).
Acute hepatic failure (1 paper, 2019). Hepatic failure refers to the inability of the liver to perform its normal synthetic and metabolic functions, which can result in coagulopathy and alteration in the mental status of a previously healthy individual. "Researchers have analyzed the level of IL-15 in patients with acute hepatic failure and have suggested that overexpression of IL-15 might cause liver injury in humans." (PMID 31269941, 2019).
Anorexia (1 paper, 2017). Lack of desire to eat (loss of appetite). "Cachexia often appears with anorexia as a result of imbalances between pro-inflammatory (e.g., TNF-α, IL-1, IL-6, interferon-gamma [IFN-γ]) and anti-inflammatory cytokines (e.g., interleukin-4 [IL-4], interleukin-12 [IL-12], interleukin-15 [IL-15])." (PMID 28177923, 2017).
anorexia nervosa (1 paper, 2025). A disorder most often seen in adolescent females characterized by a refusal to maintain a minimally normal body weight, an intense fear of gaining weight, a disturbance in body image, and, in postmenarcheal females, the development of amenorrhea. "Interleukin (IL)−6 and IL-15 are higher, and IL-7 lower, in anorexia nervosa (AN) compared with controls." (PMID 41034374, 2025). "Results reveal elevations in interleukin (IL)-6 and IL-15 and reductions in IL-7 in people with anorexia nervosa in comparison to healthy controls, and no elevations in pro-inflammatory cytokines in people with bulimia nervosa." (PMID 41034374, 2025).
aplastic anemia (1 paper, 2012). Anemia resulting from bone marrow failure (aplastic or hypoplastic bone marrow). "IL-15 on fibroblasts from human spleen regulates NK cell differentiation from blood CD34+ progenitors and IL-15 on bone marrow fibroblast-like stromal cells contributes to T cell recruitment and expansion in aplastic anemia." (PMID 22792388, 2012).
Arthralgia (1 paper, 2009). "The role of IL-15 and NK cells in the development of CHIKV arthralgia would definitively be worth investigating." (PMID 19156204, 2009). "The detection of IL-7 and IL-15 is significantly interesting with regards to the immunopathology of CHIKF since CHIKV infection has been shown to induce rapidly developing and persisting arthralgia." (PMID 19156204, 2009).
B-cell lymphoblastic leukemia (1 paper, 2024). "In studies, patients with B-cell lymphoblastic leukemia following CAR-T cell therapy presented elevated levels of IL-1α, IL-2, IL-3, IL-5, IL-6, IL-8 IL-10, IL-15, IFN- γ, procalcitonin, CRP, G-CSF, GM-CSF, and MCP-1, and their levels were linked to the severity of neurotoxicity." (PMID 39409959, 2024).
bacterial pneumonia (1 paper, 2020). Acute infection of the lung parenchyma caused by bacteria (e.g., Streptococcus pneumoniae, Haemophilus influenzae, Chlamydia pneumoniae, Mycoplasma pneumoniae, and Legionella pneumophila). "Patients with bacterial pneumonia exhibited the greatest elevation and number of cytokines in urine that differed from healthy controls; S. aureus pneumonia patients differed in all 11 cytokines with IL-4, IL-15, Gro-α, MIP-1α and SDF-1 uniquely elevated in those patients." (PMID 32770049, 2020).
brain glioma (1 paper, 2018). A malignant glioma that involves the brain. "In conclusion, novel associations with pre-diagnostic serum levels of IL-15 and IL-16 and their modification by history of diagnosis of immune-related conditions support the importance of immune alterations in the aetiology of young- and middle-age-at-onset brain glioma years before diagnosis." (PMID 30297770, 2018).
brain injury (1 paper, 2016). Acute and chronic (see also brain INJURIES, CHRONIC) injuries to the brain, including the cerebral hemispheres, CEREBELLUM, and brain STEM. "In coherence with previous literature, in our study Il-6, IL-1ra, Il-8, IL-10, IL-15, MCP-1, MIP-1β, and IP10 were selected in the first two components of PCA as strong predictors of outcome confirming their role in the pathophysiology of brain injury." (PMID 27324502, 2016).
brucellosis (1 paper, 2021). Brucellosis is a bacterial infection that spreads from animals to people via unpasteurized dairy products or by exposure to contaminated animal products or infected animals. "Genes known to be highly associated with brucellosis contain multiple SNP sites, such as TGF-β, IFN-γ, TNF-α, IL-15, and TNF-α." (PMID 34306007, 2021).
Chlamydia infection (1 paper, 2024). "We show that IFNε promotes NK cell accumulation, activation, and effector cytokine production in response to Chlamydia infection through IL-15-dependent and -independent mechanisms." (PMID 38263527, 2024).
choledocholithiasis (1 paper, 2019). Presence or formation of gallstones in the common bile duct. "In patients with obstructive jaundice or choledocholithiasis, a panel of IL-8, IL-15 and gender significantly discriminated PDAC from benign disease with an AUC of 0.830 (p < 0.0001)." (PMID 31415645, 2019). "Moreover, IL-15 levels was protective against PDAC in patients with obstructive jaundice or choledocholithiasis." (PMID 31415645, 2019). "Furthermore, biomarker panels including IL-8 and/or IL-15 showed significant diagnostic power in discriminating PDAC patients from benign disease patients with biliary pathologies, and continued show diagnostic accuracy in the presence of jaundice or choledocholithiasis." (PMID 31415645, 2019).
chorioamnionitis (1 paper, 2025). A morphologic finding indicating inflammation of the fetal sac membranes. "GM-CSF, IL-15, IL-17, IL-2, IL-2R, VEGF, and MIG concentrations were significantly higher in patients with chorioamnionitis than in those without chorioamnionitis." (PMID 41277827, 2025).
chronic fatigue syndrome (1 paper, 2015). "Prior work has shown that chronic fatigue syndrome may be associated with reduced IL-15 and, in turn, reduced natural killer cell activity." (PMID 26420016, 2015). "However, based on prior research that reported changes in CD8+ T-cell expression and function in GWI and chronic fatigue syndrome, the changes in IL-15 expression may suggest that daily fatigue is associated with an altered immune response to activity and other stressors." (PMID 26420016, 2015).
chronic hepatitis C (1 paper, 2018). "In another study, chronic hepatitis C patients presented elevated serum levels of IL-10, IFN-γ, IL-6, and IL-4, while IL-1, IL-2, IL17, IL-22, IL-13 TNF, IL-12p70, and IL-15 levels were lower in patients compared to healthy controls." (PMID 29977152, 2018).
chronic myelomonocytic leukemia (1 paper, 2023). A myelodysplastic/myeloproliferative neoplasm which is characterized by persistent monocytosis, absence of a Philadelphia chromosome and BCR/ABL fusion gene, fewer than 20 percent blasts in the bone marrow and blood, myelodysplasia, and absence of PDGFRA or PDGFRB rearrangement. "PRGN-3006, a CD33-directed CAR-T with IL-15 membrane bound, was tested in 20 R/R AML, 1 chronic myelomonocytic leukemia (CMML) with ≥5% blasts, and 3 high-risk MDS without (cohort 1) or with lymphodepletion (fludarabine 30 mg/m2 and cyclophosphamide 500 mg/m2 days −5 to −3; cohort 2)." (PMID 37892958, 2023).
clear cell renal carcinoma (1 paper, 2012). A malignant epithelial neoplasm of the kidney characterized by the presence of lipid-containing clear cells within a vascular network. "Herein, we analyzed the expression and the biological functions of IL-15 in normal renal proximal tubuli (RPTEC) and in their neoplastic counterparts, the renal clear cell carcinomas (RCC)." (PMID 22363690, 2012). "In order to shed light on the function of IL-15 in the renal human model, we investigated the expression of IL-15 receptor subunits (IL-15Rαβγ) on primary cultures of normal Renal Proximal Tubular Epithelial Cell (RPTEC) and clear cell renal carcinomas (RCC)." (PMID 22363690, 2012).
CNS leukemia (1 paper, 2017). "As described in the prior section, the cytokine IL-15 has been implicated in CNS leukemia." (PMID 28491865, 2017). "The ability of IL-15 to regulate NK cell development, survival, and activation may provide another, indirect mechanism by which IL-15 influences CNS leukemia." (PMID 28491865, 2017).
coccidiosis (1 paper, 2012). A parasitic infection caused by Coccidia. "Another study demonstrated that the recombinant protein from the Eimeria acervulina in combination with the chicken IL-15 against coccidiosis which exhibited significantly greater serum IgG antibody levels than with the recombinant protein alone in ovo." (PMID 22866758, 2012).
cystitis (1 paper, 2024). Inflammation of the urinary bladder. "A number of urinary markers have been shown to increase during pyelonephritis as opposed to cystitis (INF gamma, IL15, and chemokine ligands)." (PMID 39595148, 2024).
dermatitis herpetiformis (1 paper, 2025). "Dermatitis herpetiformis (DH), the most well-characterized neutrophilic dermatosis associated with CD, shares immunopathogenic features with PG, including IL-8 and IL-15-driven neutrophilic inflammation." (PMID 40747164, 2025).
dilatation (1 paper, 2022). "Collectively, these results are consistent in showing that the combined cardiac overexpression of IL9, IL3, IL4, IL13, and IL15 during the chronic phase of CVB3-induced VM can significantly improve the outcome of cardiac disease, reducing cardiac dilatation and dysfunction." (PMID 35508525, 2022).
ductal carcinoma in situ (1 paper, 2021). "In agreement with our findings, Cohen and colleagues who used immunoassay method for the quantitation of circulating inflammatory mediators, identified zero levels of IL-15 in invasive BC patients while its level was higher in ductal carcinoma in situ (DCIS)." (PMID 33446741, 2021).
Ebola virus disease (1 paper, 2019). "Similar cytokine patterns observed in our study in CCHF and HFRS patients, were seen also in patients with Ebola virus disease (EVD) where elevated levels of IL-1β, IL-1RA, IL-6, IL-8, IL-15, MIP-1α, MIP-1β, MCP-1, MCP-3, IP-10 and eotaxin were associated with fatal outcome." (PMID 31357521, 2019).
endometrial tumors (1 paper, 2021). "The concentration of IP-10, PDGF-AA, TGFα, fractalkine, IL-1α, IL-15, IL-13, sCD40L, VEGF, PDGF-BB, IL-17, RANTES, IL-1Ra and IL-8 trended higher in CM from endometrial tumors than that measured in CM from adjacent non-cancerous tissue." (PMID 33968059, 2021).
endophthalmitis (1 paper, 2024). An infectious process affecting the internal structures of the eye. "In an intradermal infection mice model, IL-1β, IL-6, TNF-α, and IFN-γ were produced by the lymph nodes only after MSSA infection; while in a murine model of endophthalmitis, IL-10, IL-15, IL-11, and some chemokines and receptors were significantly strongly upregulated by MRSA." (PMID 38571946, 2024).
erythroleukemia (1 paper, 2022). Acute erythroid leukemia characterised by the presence of at least 50% erythroid precursors and at least 20% myeloblasts in the bone marrow. "We first tested whether HODHBt enhanced the ability of IL-15-activated NK cells to kill the erythroleukemia K562 cell line, which lacks major histocompatibility complex (MHC) class I, making these cells a target for NK cells." (PMID 35867565, 2022).
Fulminant hepatitis (1 paper, 2012). Acute hepatitis complicated by acute liver failure with hepatic encephalopathy occurring less than 8 weeks after the onset of jaundice. "In this study, we aimed to study the role of IL-15 in a sterile APAP-induced fulminant hepatitis model in IL-15-knockout (Il15−/−) and wild-type (WT) mice." (PMID 23028657, 2012).
gingivitis (1 paper, 2024). A disorder involving inflammation of the gums; may affect surrounding and supporting structures of the teeth. "Finally, gingivitis produced changes in saliva, with salivary levels of GM-CSF, IL-6, IL-7, IL-15, IP-10, KC-like, IL-10, IL-18, MCP1, TNFα being statistically significantly higher in the saliva of CG2 dogs compared to CG1." (PMID 38521919, 2024). "According to Dunn`s multiple comparison test, dogs with DM presented statistically higher GM-CSF, IL6, IL15, and MCP1 levels as compared with CG1 (healthy gingiva), and lower KC-like chemokine as compared with CG2 (gingivitis)." (PMID 38521919, 2024).
glaucoma (1 paper, 2021). Increased pressure in the eyeball due to obstruction of the outflow of aqueous humor. "In tear samples, an increase in IL-4, IL-12, IL-15, IL-6, and IL-8 in patients with glaucoma have been reported." (PMID 34575451, 2021).
haemorrhagic fever (1 paper, 2019). "IL-15 and MCP-1 were also associated with a bad prognosis during the Crimean–Congo haemorrhagic fever." (PMID 30901952, 2019).
Headache (1 paper, 2021). Cephalgia, or pain sensed in various parts of the head, not confined to the area of distribution of any nerve. "Regarding the central tendency measures, in the comparison of the crude median values of cytokines, we observed that patients with headache had higher median values of GROa, IFN-gamma, IL-10, IL-13, IL-15, IL-17a, IL-21, IL-22, IL-27 and IL-6." (PMID 34088273, 2021).
hepatitis B (1 paper, 2023). "Infected patients with hepatitis B have also been reported to induce expression of IL-15 and its low levels." (PMID 36742132, 2023).
hepatitis C virus infection (1 paper, 2012). A viral infection caused by the hepatitis C virus. "Increased serum IL-15 level was also noted in patients with liver transplantation or hepatitis C virus infection." (PMID 23028657, 2012).
heroin addicts (1 paper, 2021). "The analysis revealed that the levels of IL-1ra, IL-1β, IL-5, IL-12p70, IL-13, IL-15, MIP-1β, bFGF, and RANTES in the plasma of heroin addicts in the AW and PW stages were not significantly different from those in the plasma of the control group subjects (data not shown)." (PMID 34489980, 2021).
hip fracture (1 paper, 2022). Traumatic or pathological injury to the hip in which the continuity of either the femoral head, femoral neck, intertrochanteric or subtrochanteric regions is broken. "Unsurprisingly, our study also observed significantly increased levels the Th1 (combination of IL-2, IFN-γ and IL-12) and T cell growth and activation factors (a combination of IL-4, IL-7, IL-9, IL-12, IL-15, GM-CSF) in the delirious hip fracture patients compared to the non-delirious group." (PMID 35641947, 2022).
hookworm infection (1 paper, 2012). "Transcription of the Th1 cytokine gene IFN-γ and the T cell proliferative cytokine gene IL-15 were also upregulated after hookworm infection." (PMID 22346753, 2012). "However, in contrast to the increased accumulation of IL-2, IL-15 and ALDH1A2, accumulation of mRNA encoding the innate Th17-inducing and stabilising IL-23 was potently suppressed by hookworm infection, potentially neutralising the impact of these Th17 promoting cytokines." (PMID 22346753, 2012). "Despite enhanced production of IL-15 and ALDH1A2, levels of IL-23 were dramatically suppressed after hookworm infection, possibly accounting for the absence of a Th17 response via suppression of antigen presenting cell function." (PMID 22346753, 2012).
hyperandrogenism (1 paper, 2022). Excessive secretion of androgens from the adrenal glands or gonads. "And there is a randomized controlled trial using BNZ-1, a selective and simultaneous inhibitor of cytokines IL-2, IL-9, and IL-15, for the treatment of hyperandrogen-induced hair loss.It shows that factors that inhibit IL-15 such as BNZ-1 have a role in the treatment of PCOS hyperandrogenism." (PMID 35250857, 2022).
hyperthyroidism (1 paper, 2025). Overactivity of the thyroid gland resulting in overproduction of thyroid hormone and increased metabolic rate. "Bayesian network analysis in the hyperthyroidism group revealed complex interrelationships among FT3, FT4, TSH, IL-15, leptin, IL-6, and TNF-α, with TSH significant regulating inflammatory responses and SMI potentially influencing pre- and post-exercise glucose levels." (PMID 41355999, 2025).
hyperuricemia (1 paper, 2021). An abnormally high level of uric acid. "On the other hand, in controls, the polymorphisms were associated with hypoalphalipoproteinemia, non-HDL cholesterol, apolipoprotein B, hyperuricemia, TNF-α, IL-6, IL-15, valvular calcification, and subclinical hypothyroidism." (PMID 33802675, 2021). "In controls, associations with hypoalphalipoproteinemia, non-HDL-C, apolipoprotein B, hyperuricemia, TNF-α, IL-6, IL-15, valvular calcification, and subclinical hypothyroidism were observed." (PMID 33802675, 2021).